SF3B4 (splicing factor 3b subunit 4)
Description:
Component of the 17S U2 SnRNP complex of the spliceosome, a large ribonucleoprotein complex that removes introns from transcribed pre-mRNAs. The 17S U2 SnRNP complex (1) directly participates in early spliceosome assembly and (2) mediates recognition of the intron branch site during pre-mRNA splicing by promoting the selection of the pre-mRNA branch-site adenosine, the nucleophile for the first step of splicing. Within the 17S U2 SnRNP complex, SF3B4 is part of the SF3B subcomplex, which is required for 'A' complex assembly formed by the stable binding of U2 snRNP to the branchpoint sequence in pre-mRNA. Sequence independent binding of SF3A and SF3B subcomplexes upstream of the branch site is essential, it may anchor U2 snRNP to the pre-mRNA. May also be involved in the assembly of the 'E' complex. Also acts as a component of the minor spliceosome, which is involved in the splicing of U12-type introns in pre-mRNAs.
Synonyms: SAP49; SF3b49; Hsh49; AFD1
Tractability: Small molecule: a structure with a bound ligand is known. PROTAC: ubiquitination databases record sites on it; its protein half-life has been measured.
Target class: Other nuclear protein
Gene: Protein-coding gene on chromosome 1 (149,923,317 to 149,927,803, reverse strand). Ensembl gene ENSG00000143368.
Subcellular location: Nucleus
Subcellular location (Human Protein Atlas): Nuclear speckles
Pathways (Reactome):
Metabolism of RNA: mRNA Polyadenylation; mRNA Splicing - Major Pathway; mRNA Splicing - Minor Pathway
Chromatin organization: CHD1 and CHD2 subfamily
Disease: Dengue Virus-Host Interactions
Gene Ontology:
Molecular function: protein binding; RNA binding; splicing factor binding; nucleic acid binding
Biological process: mRNA splicing, via spliceosome; mRNA processing; RNA splicing; RNA splicing, via transesterification reactions; spliceosomal snRNP assembly; spliceosome conformational change to release U4 (or U4atac) and U1 (or U11); U2-type prespliceosome assembly
Cellular component: nucleus; precatalytic spliceosome; spliceosomal complex; U11/U12 snRNP; U12-type catalytic step 2 spliceosome; U12-type precatalytic spliceosome; U12-type spliceosomal complex; U2-type catalytic step 1 spliceosome; U2-type precatalytic spliceosome; U2-type spliceosomal complex; nucleoplasm; U2 snRNP
Genetic constraint (gnomAD): Loss-of-function variants: 3 observed, 29.89 expected, observed/expected ratio (o/e) 0.1, 90% interval 0.045 to 0.26. The upper end of that interval is the gene's LOEUF score, 0.26, which puts it in group 1 of 6, group 1 being the genes least tolerant of losing a copy. Missense variants: 247 observed, 504.76 expected, observed/expected ratio (o/e) 0.49, 90% interval 0.44 to 0.54. Synonymous variants: 200 observed, 190.35 expected, observed/expected ratio (o/e) 1.05, 90% interval 0.94 to 1.18.
Gene-disease validity (ClinGen):
ClinGen rates the evidence that SF3B4 causes each of these diseases.
SF3B4-related acrofacial dysostosis (autosomal dominant): Definitive. A congenital malformation syndrome characterized by mandibulofacial dysostosis and anterior upper-limb defects, though occasionally, lower-limb defects have also been reported.
Homologues: Orthologues: chimpanzee SF3B4 (100% identical), macaque SF3B4 (100% identical), rabbit SF3B4 (99% identical), guinea pig SF3B4 (99% identical), mouse Sf3b4 (99% identical), pig SF3B4 (99% identical), dog SF3B4 (99% identical), rat Sf3b4 (98% identical), zebrafish sf3b4 (78% identical), tropical clawed frog sf3b4 (76% identical), Caenorhabditis elegans sap-49 (59% identical), Drosophila melanogaster Spx (58% identical). Paralogues in human: PABPC1 (20% identical), PABPC3 (20% identical), ELAVL2 (20% identical), ELAVL4 (20% identical), ELAVL1 (19% identical), ELAVL3 (19% identical), RBMS3 (19% identical), RBMS1 (19% identical), PABPC1L (19% identical), PABPC4 (18% identical), PUF60 (18% identical), SYNCRIP (18% identical), and 12 more.
Diseases named in the same sentence as SF3B4 in open-access papers:
SF3B4 is named in the same sentence as 44 diseases in open-access papers, as found by Europe PMC text mining. Sharing a sentence is not in itself a finding about the gene and the disease. The quoted sentences say what the papers report.
Nager syndrome (23 papers, 2016 to 2025). Nager syndrome, also called Nager acrofacial dysostosis (NAFD) is a congenital malformation syndrome characterized by mandibulofacial dystosis (malar hypoplasia, micrognathia, external ear malformations) and variable preaxial limb defects. "For instance, SF3B1 mutations cause skeletal abnormalities, while SF3B4 mutations lead to Nager syndrome." (PMID 40608414, 2025). "The majority of the described causes of Nager syndrome include pathogenic variants in the SF3B4 gene, which encodes a component of the spliceosome; therefore, the syndrome belongs to the spliceosomopathy group of diseases." (PMID 38254920, 2023). "The major causes of Nager syndrome are pathogenic variants in the Splicing Factor 3b Subunit 4 (SF3B4) gene, which encodes a component of the spliceosome." (PMID 38254920, 2023). "Mutations in the SF3B4 gene cause various diseases, including Nager syndrome (OMIM#154400), a rare congenital disorder characterized by craniofacial and limb defects." (PMID 36293251, 2022). "Regarding SF3B4, this gene encodes one of the four subunits of the splicing factor 3B and mutations in this gene have been found in families affected by Nager syndrome." (PMID 35646913, 2022). "In some cases, these factors are involved in general spliceosome function, for example SF3B4, which is mutated in Nager Syndrome." (PMID 33013468, 2020). "Clinical diagnosis of Nager syndrome, which can be caused by deletions encompassing SF3B4 gene, is possible prenatally." (PMID 32185046, 2020). "Variants in the SF3B4 gene that encodes a splicing factor 3B subunit 4 are found in about half of the patients clinically diagnosed with Nager syndrome." (PMID 33262786, 2020). "Heterozygous loss-of-function variants in SF3B4 are a known cause of Nager syndrome, which is consistent with the patient’s described clinical features." (PMID 29293505, 2018). "We found that mutations in SF3B4 produce Rodriguez syndrome, further demonstrating that it is allelic with Nager syndrome." (PMID 27622494, 2016). "We identified heterozygosity for SF3B4 mutations in Rodriguez syndrome, confirming that the phenotype is a dominant disorder that is allelic with Nager syndrome." (PMID 27622494, 2016). "In summary, the current study identified heterozygosity for SF3B4 mutations in one case of Rodriguez syndrome and second case with a phenotype intermediate between Rodriguez and Nager syndromes." (PMID 27622494, 2016). "Nager syndrome is caused by a mutation in the SF3B4 gene located on the 1q12-q21 chromosome." (PMID 40041258, 2023). "Importantly, emerging evidence suggests that the dysregulation of SF3B4 expression by gene mutations or other factors has been implicated in various diseases, including tumorigenesis and Nager syndrome (NS)." (PMID 36639679, 2023). "The working clinical diagnosis of Fryns-like Syndrome was changed when a molecular diagnosis was made by ES, parent-child trio analysis revealing a de novo variant in SF3B4 (c.1175dupC, p.(Pro393fs)), a gene in which pathogenic variants are known to cause Nager syndrome." (PMID 31345272, 2019). "Haploinsufficiency for SF3B4 is considered to be the major cause of Nager syndrome." (PMID 27622494, 2016). "As SF3B4 is frequently mutated in patients with Nager syndrome and it had been suggested that Rodriguez syndrome might be an allelic disorder, we determined the sequences of SF3B4 in the two cases." (PMID 27622494, 2016). "Furthermore, a case with a phenotype intermediate between Rodriguez and Nager syndromes has been shown to have an SF3B4 mutation." (PMID 27622494, 2016). "For instance, splicing factor 3b subunit 2 (SF3B2) and splicing factor 3b subunit 4 (SF3B4) are associated with craniofacial microsomia (MIM:164210; SyCL/P), and Nager syndrome (MIM:154400; SyOFC), respectively." (PMID 41427026, 2025).
Nager syndrome (continued). "SF3B4 is a core subunit of the splicing factor 3b (SF3B) complex, and an imbalance of SF3B4 involved in the occurrence of many diseases, such as Nager syndrome and tumours." (PMID 38317200, 2024). "The researchers proposed that the haploinsufficiency of SF3B4 played a role in the pathogenesis of Nager syndrome, although the specific splicing mechanism is still being investigated." (PMID 37511171, 2023). "Although SF3B1 has been the primary focus of many U2 snRNP splicing-related diseases, there have been studies that revealed the impact of haploinsufficiency of SF3B2 and SF3B4 on the development of craniofacial microsomia and Nager syndrome, respectively." (PMID 37511171, 2023). "Sf3b4-knockdown Xenopus embryos, modelling haploinsufficiency of the U2 snRNP component SF3B4 in Nager syndrome (NS), revealed reduced expression of a number of NCC marker genes at the neural plate border associated with neural plate broadening." (PMID 32735620, 2020). "Importantly, non‐penetrance has also been previously documented for SF3B4 (Nager syndrome) and SNRPB (cerebro–costo–mandibular syndrome), indicating that it is not a novel observation for spliceosome genes." (PMID 41427026, 2025). "Approximately one third of studied Nager syndrome patients do not have pathogenic variants in the SF3B4 gene." (PMID 38254920, 2023). "Downregulating or depleting human SF3b4 resulted in various diseases, such as tumorigenesis and Nager syndrome (NS) that is characterized by defective craniofacial formation." (PMID 32083075, 2020). "In a sporadic female case from family no 4, we identified the heterozygous variant in the SF3B4 gene causing Nager syndrome (MIM:54400)." (PMID 33262786, 2020). "A resulting change in clinical diagnosis may result, as illustrated by our findings with SF3B4 and Nager syndrome." (PMID 31345272, 2019). "The clinical variability in expression across Nager syndrome cases with defects in SF3B4 does suggest that modifiers can influence the phenotype, so it may be that small differences in splicing activity could contribute measureably to phenotypic expression." (PMID 27622494, 2016). "Similarly, mutations in the gene encoding the SF3B4 protein (also known as SAP49), a component of the U2 snRNP, have been found to produce Nager syndrome (OMIM 154400)." (PMID 27622494, 2016). "Splicing factor 3B subunit 4 (SF3B4) plays important functional roles not only in pre-mRNA splicing, but also in the regulation of transcription, translation, and cell signaling, and its dysregulation contributes to various diseases including Nager syndrome and tumorigenesis." (PMID 36639679, 2023). "However, it is noteworthy that a case of Nager syndrome with a de novo deletion at chromosome 1q21.2 that covers SF3B4 has been described, supporting SF3B4 haploinsufficiency as the primary driver of the craniofacial and limb defects observed in these acrofacial dysostosis phenotypes." (PMID 27622494, 2016). "It was previously considered allelic to Nager syndrome (AFD1), with an intermediate SF3B4 phenotype having also been reported." (PMID 40723430, 2025). "Rodriguez syndrome has been proposed to be a severe form of Nager syndrome, a non-lethal AFD that results from mutations in SF3B4, a component of the U2 small nuclear ribonucleoprotein particle (U2 snRNP)." (PMID 27622494, 2016). "Rodriguez syndrome has been proposed to be a severe form of Nager syndrome, a non-lethal AFD that results from mutations in SF3B4, a component of mRNA splicing machinery needed for proper maturation of primary transcripts." (PMID 27622494, 2016).
hepatocellular carcinoma (15 papers, 2020 to 2026). A malignant tumor that arises from hepatocytes. "SF3B4 promotes cell proliferation and metastasis, and acts as an early-stage diagnostic marker in hepatocellular cancer, and SF3B4 could facilitate lymphatic progression of esophageal cancer." (PMID 35210412, 2022). "Furthermore, SF3B4 outperformed the existing diagnostic markers for hepatocellular carcinoma, namely glypican 3 (GPC3), glutamine synthetase (GS), and heat-shock protein 70 (HSP70) and demonstrated its potential as a reliable diagnostic marker for early-stage hepatocellular carcinoma." (PMID 37875914, 2023). "In hepatocellular carcinoma, splicing factor 3B subunit 4 (SF3B4), a component of the spliceosome, facilitates the generation of KLF4 exon-skipping isoforms and contributes to the malignant transformation and growth of hepatocytes." (PMID 40552304, 2025). "The expression of SF3B4 was shown to be increased in hepatocellular carcinoma compared to that in normal tissues." (PMID 38168564, 2024). "In hepatocellular carcinoma, the SF3B4 knockdown induced the inactivation of p27 by skipped exon, alternating the splicing of KLF49." (PMID 38168564, 2024). "In this respect, KLF4 exon 3 has been recently proposed to be a prominent SF3B4 target, potentially acting in early-stage hepatocellular carcinomas." (PMID 32664474, 2020). "For example, the upregulation of SF3B4 promotes tumorigenesis in hepatocellular carcinoma (HCC), esophageal squamous cell carcinoma (ESCC), and ovarian cancer (OC), whereas its downregulation or depletion results in pancreatic cancer and breast cancer in NS patient." (PMID 36639679, 2023). "SF3B4 has been reported to be up-regulated in hepatocellular carcinoma." (PMID 37875914, 2023). "SF3B4 promotes hepatocellular carcinoma progression by regulating KLF4." (PMID 35210412, 2022). "By using hepatocellular carcinoma (HCC) as a model, this study illustrates the role of SF3B4 as an oncogenic factor in HCC, highlighting its potential as a pan-cancer therapeutic target and diagnostic biomarker." (PMID 41294857, 2025). "For example, miR-133b inhibits SF3B4 mRNA translation, leading to a disruption of SF3B4-regulated AS and, limitation in hepatocellular carcinoma (HCC) cell proliferation and metastasis." (PMID 40129920, 2025). "For instance, in hepatocellular carcinoma (HCC), miR-133b represses the translation of SF3B4 mRNA to disrupt SF3B4-regulated AS, inhibiting cell proliferation and metastasis." (PMID 35427215, 2022). "On the other hand, overexpressing SF3b4 can also promote tumorigenesis in hepatocellular carcinoma (HCC), suggesting an essential role of SF3b4 in cell growth." (PMID 32083075, 2020). "Moreover, in HCC (hepatocellular carcinoma), miRNA-133b inhibits the translation of SF3B4 (splicing factor 3b subunit 4) mRNA through partial complementation with its 3’UTR to decrease SF3B4-mediated AS, repressing cell proliferation and metastasis." (PMID 33407694, 2021). "Aberrant expression of SF3B4 was demonstrated to modulate the expression of cell cycle and EMT proteins through spliceosome effects on the tumor suppressor kruppel-like factor 4 (KLF4) in hepatocellular carcinoma (HCC)." (PMID 32346127, 2020).
ovarian carcinoma (7 papers, 2022 to 2024). A malignant neoplasm originating from the surface ovarian epithelium. "Although we validated that SETDB1 promoted ovarian cancer progression by promoting the transcription of SF3B4, our study still has several limitations." (PMID 38317200, 2024). "The results revealed that the expression of SF3B4 mRNA decreased notably after SETDB1 knockdown in ovarian cancer cells." (PMID 38317200, 2024). "Our previous research has shown that down-regulation of SF3B4 suppresses the proliferative ability and mobility of ovarian cancer cells." (PMID 38317200, 2024). "SF3B4 is a core splicing factor and our research showed that SF3B4 promotes ovarian cancer progression by improving the splicing efficiency of RAD52." (PMID 38317200, 2024). "Recent research has revealed the predictive significance of TMX1 and SF3B4 in ovarian cancer, as well as their roles in proliferation and motility, respectively." (PMID 39309198, 2024). "Its high expression can transcriptionally activate SF3B4 and then promote the proliferation and metastasis of ovarian cancer." (PMID 38317200, 2024). "SETDB1 promoted ovarian cancer progression by upregulating the expression of SF3B4 and inhibiting the tumour immunity." (PMID 38317200, 2024). "SF3B4 has exhibited significant upregulation in ovarian cancer and a correlation with unfavorable patient prognosis." (PMID 37875914, 2023). "Studies have shown that SF3B1, SF3B2, and SF3B3 can regulate target gene expression by alternative splicing to promote cancer progression, also SF3B3 controls AS in renal cancer and SF3B4 in ovarian cancer by regulating AS of RAD52." (PMID 37091785, 2023). "SF3B is a component of the U2 small nuclear ribonucleoprotein (snRNP), known to control AS in renal cancer and SF3B4 in ovarian cancer by regulating AS of RAD52." (PMID 37091785, 2023). "Similarly, SF3B4 knockdown also impaired the effect of SETDB1 to promote the mobility of ovarian cancer cells." (PMID 38317200, 2024). "SF3B4, an important subunit of SF3B, was found to be intimately with the poor prognosis and facilitated the proliferation and invasion abilities of ovarian cancer cells in our previous study." (PMID 35853859, 2022). "SF3B4 has been shown to act as an oncogene by modulating the alternative splicing of RAD52, thereby facilitating the proliferation, migration, and invasion of ovarian cancer cells." (PMID 37875914, 2023). "However, as a classical splicing factor, the expression of SF3B4 is not clear, and its biological function needs to be further clarified in ovarian cancer (OC)." (PMID 35210412, 2022).
acrofacial dysostosis (4 papers, 2016 to 2024). "Similarly, in the data presented here, two SF3B4 mutations that were both predicted to result in SF3B4 molecules with altered and extended carboxyl-termini, produced similar but more severe acrofacial dysostosis phenotypes, including one case with the lethal Rodriguez syndrome phenotype." (PMID 27622494, 2016).
pancreatic cancer (4 papers, 2020 to 2023). "Further studies showed that overexpression of SF3b4 in pancreatic cancer cells inhibited cell growth and motility, while suppressing SF3b4 expression promoted the proliferation and migration of pancreatic cancer cells." (PMID 32083075, 2020). "Results obtained from these studies will facilitate a better understanding of human diseases caused by the malfunction of SF3b4, such as NS, HCC, and pancreatic cancer in the future." (PMID 32083075, 2020). "In contrast, SF3B4 acts as a cancer suppressor in pancreatic cancer." (PMID 35210412, 2022). "The expression of SF3b4 was significantly decreased in pancreatic cancer cells." (PMID 32083075, 2020). "However, SF3B4 inhibits growth and migration abilities of pancreatic cancer cells." (PMID 35210412, 2022).
breast carcinoma (3 papers, 2020 to 2025). "There are 81 key genes shared by all stages, among which RPL17, CCNB1, and SF3B4 are genes that are highly (with degrees >25) related to breast cancer." (PMID 32461838, 2020). "Additionally, SF3B4 was shown to mediate the packaging of miR-216a-5p into EXOs in DOX-treated breast cancer cells." (PMID 40360476, 2025).
cervical cancer (3 papers, 2022 to 2024). A primary or metastatic malignant neoplasm involving the cervix. "SF3B4 has been reported to enhance the proliferation and invasion of cervical cancer cells, thereby promoting their malignant behavior." (PMID 37875914, 2023). "Collectively, these findings underscore the oncogenic role of SF3B4 in cervical cancer by virtue of its regulatory influence on SPAG5 splicing." (PMID 37875914, 2023). "SF3B4 mRNA expression was higher in CC patients with copy number amplification than in nonamplified samples, and SF3B4 genomic amplification contributed to its high mRNA expression in cervical cancer tissues and cell lines." (PMID 35853859, 2022).